RUNX1 (RUNX family transcription factor 1)
Diseases named in the same sentence as RUNX1 in open-access papers (continued):
Sharing a sentence is not in itself a finding about the gene and the disease.
tumor (continued). "Interestingly, we found super-enhancers near not only oncogenes but also tumor suppressor genes (IKZF1, LEF1, RUNX1), implying that not all super-enhancer associated genes contribute to tumor progression." (PMID 30304769, 2018). "However, little is known of Runx1 oncogenic or tumor suppressor activities in solid tumors." (PMID 28407681, 2017). "Thus decreased Runx1 with tumor progression correlates with EMT." (PMID 28407681, 2017). "Runt-related transcription factor 1(RUNX1), a key factor in hematopoiesis that mediates specification and homeostasis of hematopoietic stem and progenitor cells (HSPCs), is also overexpressed in several solid human cancers, and correlated with tumor progression." (PMID 29245924, 2017). "Furthermore, these data strongly suggest that Foxp3 and Runx1 protein interaction could determine Runx1 tumor promotion transcriptional activity in mammary epithelial cells." (PMID 26735887, 2016). "Moreover, reduced Runx1 transcriptional activity decreases tumor cell migration properties." (PMID 26735887, 2016). "Runx1 may be phosphorylated by the elevated MEK signaling to initiate the tumor formation process." (PMID 26697518, 2015). "Combined deletion of Runx1 and Runx2 further resulted in mammary cells becoming exquisitely sensitive to WNT-driven transformation, with expedited emergence of multiple tumours." (PMID 42092177, 2026). "Further functional studies were required to elucidate the mechanisms by which RUNX1 and USF2 impact fibroblast subpopulations and tumor biology." (PMID 39870619, 2025). "Consistent with the tumor-promoting role of CAF-FAP, functional enrichment analysis of RUNX1-targeted genes pointed to those involved in increased fibroblast proliferation, cell migration, and inflammation." (PMID 39870619, 2025). "These divergent effects were underpinned by organ-biased differences in the tumor cells’ chromatin state that emerged in the premalignant pancreas and were distinguished by the dominance of KLF4 versus RUNX1 transcription factors." (PMID 40999053, 2025). "In T-ALL, the transcription factors TAL1, GATA3, and RUNX1 form a positively connected self-regulatory loop that regulates T-cell homeostasis and directly activates MYB to facilitate tumor progression." (PMID 40083704, 2025). "In summary, RUNX1 significantly enhanced liver and lung metastases in CRC models, highlighting its role in tumor aggressiveness." (PMID 39309442, 2024). "To explore the heterogeneity of T cell compartment and the characteristics of tumor-reactive T cells, we collected BM T cells from 5 newly diagnosed AML patients with RUNX1::RUNX1T1 and performed scRNA-seq and scV(D)J-seq." (PMID 39243082, 2024). "In iCCA, a study reported that lncRNA-NEF was downregulated in the tumor tissues, and upregulated lncRNA-NEF expression repressed cell migration and invasion by inhibiting runt-related transcription factor 1 (RUNX1)." (PMID 38892191, 2024). "Significantly, a positive correlation was observed between the protein expression levels of RUNX1 and MUC13 in CRC tumor tissues." (PMID 39309442, 2024). "Macrophage‐specific and systemic inhibition of Runx1 effectively blocks MMT‐driven tumor formation in vivo, representing a druggable therapeutic target to eliminate tumor‐promoting CAFs in NSCLC patients." (PMID 37967345, 2024). "The expression of the RUNT-related transcription factor RUNX1 is inhibited by the knockdown of HCP5, and RUNX1 binds to microRNA-139 to affect the metastasis and proliferation of tumor cells." (PMID 38071681, 2024).
tumor (continued). "Other major potential tumor growth factors, such as POU2F2, RUNX1, ERG, REL, and JUN, were also relatively increased in the low TEX-score group." (PMID 38629071, 2024). "In the tumor tissue of AML patients, the presence of RUNX1::RUNX1T1 and CBFB::MYH11 fusions positively affects the course of the disease." (PMID 38392574, 2024). "The Runt-related transcription factor 1 (RUNX1) plays a dual role as both an oncogene and a tumor suppressor in various cancers, including CRC." (PMID 39309442, 2024). "This study provides the first evidence of the regulatory role of Runx1 in MMT‐driven CAF formation and emphasizes its potential as a therapeutic target for MMT‐driven tumor growth." (PMID 37967345, 2024). "To evaluate the characteristics of tumor-reactive T cells, we collected bone marrow (BM) T cells from newly diagnosed AML patients with RUNX1::RUNX1T1 as examples for paired single-cell RNA sequencing and single-cell V(D)J sequencing." (PMID 39243082, 2024). "By drawing on experiences from solid tumor research, we identified tumor-reactive T cells with unique phenotypes in AML, especially AML with RUNX1::RUNX1T1, and detected ADGRG1 as their marker." (PMID 39243082, 2024). "IHC analysis of 12 pairs of randomly selected CRC samples showed a positive correlation between the proportion of RUNX1 positive areas and CD68 (P < 0.0001), CD163 (P = 0.0002) positive areas in tumor." (PMID 38419056, 2024). "AR activation by dihydrotestosterone (DHT) induces RUNX1 gene expression in vitro and in vivo in AR+-TNBC PDX tumor samples." (PMID 36766786, 2023). "Overexpression of RUNX1 is seen in many cancers, and the extent of expression is significantly related to the extent of CAF infiltration in tumor tissue." (PMID 38275375, 2023). "Subsequent transcriptomic and epigenomic data integration has allowed us to reveal subtype‐specific molecular pathways governed by AP‐1, SMAD3 and RUNX1/RUNX2 transcription factors (TF) in both pd‐GBSCs and bulk tumours." (PMID 37357610, 2023). "The RUNX family of transcription factors, including RUNX1, RUNX2, and RUNX3, are key regulators of development and can function as either tumor suppressors or oncogenes in cancer." (PMID 37190015, 2023). "In parallel there was a dramatic elevation in USP10 and RUNX1 protein levels in recurrent MES GBM tissues, in comparison to primary PN tumor ones." (PMID 36949071, 2023). "To explore the role of RUNX1 in tumor progression and the immune response of LGG, we explored the highest correlation gene with RUNX1 transcript level through UALCAN analysis and identified IFNGR2 as the target gene." (PMID 36321611, 2023). "We found RUNX1 was well overlapped with BiP, PERK and eIF2α in the tumor cells relatively to other ER stress related markers." (PMID 37697370, 2023). "We compared the transcriptome data between normal samples and GBM tumor samples, which indicated that ANXA1, PDPN, COL6A1, BCL3, RUNX1, and WWTR1 were upregulated and compared to normal samples, BCL11A was downregulated in GBM tumor samples." (PMID 37434432, 2023). "In addition, excessive expression of RUNX1 under certain experimental conditions may functionally mimic tumor-suppressive RUNX3 (as described later) depending on the similarity of the consensus sequence for DNA binding, suggesting the presence of functional redundancy." (PMID 36831211, 2023). "After the GSEA pathway enrichment analysis, the IL2-STAT5 pathway was enriched by the higher expression of RUNX1 and IFNGR2, which were involved in cell proliferation, migration, invasion, and tumor immunity." (PMID 36321611, 2023). "IGF2BP1 is specifically expressed in ETV6::RUNX1 positive B-ALL cell lines and its knockout reduces tumor cell proliferation and prednisolone resistance in Reh cell line." (PMID 37670323, 2023). "RUNX1 was shown to have a synergistic effect on HNF3 function and in promoting E-cadherin expression, which explains another mechanism for its tumor suppressor properties." (PMID 36831308, 2023).
tumor (continued). "Altogether, these results indicate that RUNX1 modulates ER stress via the PERK/eIF2α axis, driving adaptive capacity of tumor cells and promoting acquisition of GEM resistance in PDAC." (PMID 37697370, 2023). "We further explored the relationship between the different RUNXs expression and the abundance of tumor-infiltrating lymphocytes (TILs) through TISIDB analysis and found that RUNX1, RUNX2, and RUNX3 were positively correlated with TILs." (PMID 36321611, 2023). "In its tumor-suppressive role, RUNX1 is known to negatively regulate the ARF transcript by the aberrant chromosome translocation-mediated fusion protein of RUNX1." (PMID 36831211, 2023). "RUNX1 modulates the PERK/eIF2α signaling through BiP, conferring selective advantage for tumor cells under stress." (PMID 37697370, 2023). "The family of Runt-related (RUNX) genes (RUNX1, RUNX2, and RUNX3) is crucial for the different tumour types’ development and progression." (PMID 37759525, 2023). "Three RUNX transcription factors, RUNX1, RUNX2, and RUNX3, along with their cofactor CBFβ, exert tumor-related functions in a context-dependent manner." (PMID 37190031, 2023). "The results revealed that the expression levels of RUNX1, RUNX2, RUNX3 were higher in tumor tissues than in normal tissues, especially the expression of RUNX2 and RUNX3." (PMID 36092942, 2022). "7.44 was shown to specifically interfere with NHR2, restore gene expression down-regulated by RUNX1/ETO, inhibit the proliferation of RUNX1/ETO-depending SKNO-1 cells, and reduce the RUNX1/ETO-related tumor growth in a mouse model." (PMID 35986043, 2022). "Alternatively, genetic depletion of L1CAM, serpin B1, ARP2/-3, RUNX1, or ITGA5 in tumor cells has been demonstrated to attenuate vessel co-option." (PMID 35951441, 2022). "We also investigated at the pan-cancer and inter-tumor heterogeneity of RUNX gene family expression, and found that RUNX1 and RUNX3 were highly expressed at the pan-cancer level, whereas RUNX2 was modestly expressed." (PMID 35522574, 2022). "With IPMN progression, tumor stemness increased continuously, and KRAS, ERBB3, RUNX1, and ELF3 are essential driver genes affecting tumor stemness." (PMID 36090038, 2022). "Gene group 2 displayed a significant upregulation of E2F transcription activators (E2F1, E2F2, E2F3, and E2F6) and tumor-specific transcription factors (MYCN, RUNX1, and GABPB1) in advanced Rb." (PMID 35626705, 2022). "Based on our findings, we discovered that circRUNX1, which is derived from RUNX1 pre-mRNA, was highly expressed in ESCC tissues and cell lines and was related to tumor differentiation grade and TNM stage." (PMID 36522683, 2022). "Previously, we have shown that the repression of NOTCH3 is one of the mechanisms of the tumor suppressive functions of CBFB and RUNX1." (PMID 33945523, 2021). "Immunohistochemical staining was used to determine the expression levels of RUNX1, ARP2/3, TSP1, and TGFβ1 in tumor sections, which we found lower levels of their expression in RUNX1-knockdown specimens than their control counterparts." (PMID 34376784, 2021). "To analyze the expression level of RUNX1 in GBM, we first used GEPIA tool and found that RUNX1 was significantly upregulated in GBM tumor samples as compared to the normal brain tissues." (PMID 34895074, 2021). "We also performed IHC staining of other top-ranked TFs including SIX1, RUNX1, and SOX4 and again found higher expression level of these TFs in tumor tissues." (PMID 34001209, 2021). "To elucidate the effect of RUNX1 expression on survival of NSCLC patient, we analyzed the expression of RUNX1 using immunohistochemistry of formalin-fixed paraffin-embedded tumor tissues from 409 NSCLCs." (PMID 32498288, 2020). "RUNX1, the predominant RUNX family member, which has central roles in both neoplasia and normal development, also potentially functions as tumor oncogenes or suppressors on the basis of cellular context." (PMID 32662828, 2020).
tumor (continued). "TCGA dataset mining was performed using UALCAN to shown that abnormal expression of the hub genes, including CDK1, VEGFA, PRDM10, RUNX1, CDK6, HSP90AA1, and MYC, were significantly up-regulated between ESCA primary tumor and normal tissues." (PMID 32662828, 2020). "We also demonstrated the co-operative function of RUNX1 and FOSL2 in maintaining the expression of SNAI2, a key mediator of epithelial–mesenchymal transition and tumor dissemination." (PMID 30903020, 2019). "As clinical behavior of tumor stage pT1 is similar to pT2, and pT3 to pT4, we analyzed the significance of PRMT1, RUNX1, ZEB1 and TWIST 1 expression in pT1/pT2 versus pT3/pT4 stage group." (PMID 31655611, 2019). "For instance, the tumor suppressor genes WT1 and PI3KR1 were hypermethylated and underexpressed in high E-score tumors whereas RUNX1 and PBRM1 were hypermethylated and underexpressed in high S-score tumors." (PMID 30902996, 2019). "On the other hand, PRMT1 activates RUNX1, that prevents EMT and therefore, RUNX1 serves as a tumor suppressor in various cancers." (PMID 31655611, 2019). "PRMT1 expression in tumor tissue was compared to the IHC expression of EMT-related transcription factors (ZEB1, RUNX1, and TWIST1) and cell surface markers (ß-catenin, N- and E-cadherin)." (PMID 31655611, 2019). "Herein we report that RUNX1 regulates the ErbB2/HER2 signaling pathway in gastric cancer cells through transactivating SOS1 expression, rendering itself an ideal target in anti-tumor strategy toward this cancer." (PMID 29686309, 2018). "Out of 16 analyzed TNBC tumors, six, three, two, and one tumor harbored SVs involving RB1, KMT2C, PTEN, or RUNX1, respectively." (PMID 28636652, 2017). "In Addition, we also noticed that two very recent studies showing that pharmacological inhibition of LSD1 has significant anti-tumor effects in MV4-11(MLL-AF4) systemic model and Kasumi-1(RUNX1(AML1)/CBFA2T1(ETO)) xenograft model." (PMID 29156705, 2017). "In this study, we confirmed that the transcription factor, RUNX1, is upregulated in PDAC and plays many roles supporting tumor progression." (PMID 29245924, 2017). "Runx1 transcriptional activity was reduced by expression of the dominant-negative (DN) form of Runx1 in LM3 and MDA-DB-231 tumor cells." (PMID 26735887, 2016). "Runx1 is able to promote RSPO3 gene expression and inhibit GJA1 gene expression on tumor epithelial cells, depending on Foxp3 availability." (PMID 26735887, 2016). "Accordingly, RNA-seq and immunohistochemical analyses demonstrate an ER-dependent correlation between RUNX1 and AXIN1 in tumour biopsies." (PMID 26916619, 2016). "Nuclear HES1 was seen to be increased in CYLD defective tumours, but the difference from control epidermis was smaller than for LEF1 and RUNX1 (p = 0.027)." (PMID 25565632, 2014). "These genes (RUNX1, RUNX2 and RUNX3) exhibit context-dependent oncogenic and tumour-suppressive properties through pertinent effects on cell growth and viability." (PMID 24626992, 2014). "Thus, leukemic cells that express AF4-MLL produce an additional coactivator complex that may push the balance toward RUNX1 functioning as a general activator, and this may have an impact on whether RUNX1 is a tumor suppressor or an oncogene in different cell types." (PMID 23352661, 2013). "We also observed that a number of genes with tumor suppressor function (GPRC5A, ELF1, NAB2, Sema4D, ACPP, MAP2, RUNX1) persistently remained downregulated in response to radiation exposure." (PMID 23216862, 2012). "The SP1, MAX, RUNX1 and STAT3 sub-networks are involved in both early and late stages of the tumor but are expressed with different gene expressions." (PMID 20025723, 2009).
tumor (continued). "In addition, IGV visualization confirmed significant enrichment of eccDNA at genomic loci of tumor-related genes such as FLT3, RUNX1, CD33, and HMGB1." (PMID 41278279, 2025). "Additionally, dynamic IPA site usage was observed in well-known tumor suppressor genes, including TSC1, HSD17B2, CD58, RUNX1 and INPP4B." (PMID 41218079, 2025). "The post-transcriptional silencing of RUNX1 by MIR215 might contribute to the enhanced invasive and proliferative capacities of tumor cells." (PMID 40176817, 2025). "Previously, we identified the small-molecule inhibitor 7.44, which interferes with NHR2 domain tetramerization of RUNX1/ETO, restores gene expression down-regulated by RUNX1/ETO, inhibits proliferation, and reduces RUNX1/ETO-related tumor growth in a mouse model." (PMID 40399488, 2025). "In the present study, we unexpectedly discovered that PDGF-BB stimulated the expression of RUNX1 in CRC cells and promoted its malignant phenotype of migration and invasion in vitro, thus forming a positive feedback loop of RUNX1 and PDGF-BB to promote tumor angiogenesis and metastasis." (PMID 38419056, 2024). "These database findings corroborate the dual prognostic implications of RUNX1, underline the primary negative prognostic influence of RUNX2, and validate the tumor-suppressive role of RUNX3." (PMID 38430423, 2024). "RUNX1 was overexpressed in COAD and its expression level increases with tumor progression." (PMID 38886545, 2024). "Notably, RUNX1 was upregulated, while RUNX3 was downregulated in COAD tumor tissues, with statistical significance." (PMID 39822248, 2024). "Targeting TGFB1/SMAD3/RUNX1 signaling inhibits MMT-driven CAF and tumor formation in NSCLC." (PMID 39201328, 2024). "Importantly, we demonstrated that Runx1 was Smad3‐dependently up‐regulated in the TGF‐β1‐stimulated BMDMs in vitro and MMTs of LLC‐tumor in vivo." (PMID 37967345, 2024). "Similarly, upon quantifying tumor weights, the findings distinctly emphasized the inhibitory effect of MUC13 downregulation on the tumorigenic capabilities of RUNX1 overexpression." (PMID 39309442, 2024). "Importantly, we have shown that inhibition of Runx1 effectively blocked MMT in LLC tumors in vivo and TGF‐β1‐stimulated BMDMs in vitro, which significantly contributed to the suppression of tumor growth in LLC‐bearing mice." (PMID 37967345, 2024). "Our group has shown that RUNX1 promotes TNBC cell migration and regulates tumor gene expression." (PMID 36766786, 2023). "Though RUNX1 was identified the oncogenic role in tumor proliferation and distant metastases, and also a prognostic marker for PDAC owing to it related to shorter survival; however, the versatile roles of RUNX1 in PDAC are not well known." (PMID 37697370, 2023). "Our group showed that RUNX1 regulates R-Spondin 3 (RSPO3), promoting tumor growth and motility." (PMID 36766786, 2023). "On the contrary, RUNX1 could promote proliferation in glioblastoma by activating the MAPK signaling pathway, thus promoting tumor invasion, metastasis and angiogenesis." (PMID 38057816, 2023). "Silencing of RUNX1 could attenuate resistance in GEM-resistant cell line, and its inhibitor Ro5-3335 displayed an enhanced effect in inhibiting tumor growth, combined with GEM treatment, in PDX mouse models and GEM-resistant xenografts." (PMID 37697370, 2023). "We also detected five mutations (ALOX2B, JAK1, PGR, RUNX1, SOX1) in the HGSOC41.1 tumor sample but not in the corresponding PDO." (PMID 37202753, 2023). "A characteristic feature of tumor cells in TI-related AML is the presence of balanced chromosomal translocations, most often involving the KMT2A gene (also known as MLL) at 11q23.3 and the RUNX1 gene (also known as AML1) at 21q22.1." (PMID 36077220, 2022).